HSF1 (heat shock transcription factor 1)
Diseases named in the same sentence as HSF1 in open-access papers (continued):
Sharing a sentence is not in itself a finding about the gene and the disease.
chronic lymphocytic leukemia (5 papers, 2015 to 2022). "High levels of heat shock protein 70 (Hsp70) in chronic lymphocytic leukemia cells were found to express high levels of phospho-Akt at Ser473, thereby inducing a strong activation of HSF1." (PMID 35370703, 2022). "Additionally, the expression level of HSF1 was observed to be enhanced in chronic lymphocytic leukemia (CLL) and decreased in patients responding to in the rituximab–bendamustine protocol, which supports its potential to be a biomarker for efficacy prediction." (PMID 36069792, 2022). "In this work, we demonstrated an involvement of the HSP70/HSF1 axis in ibrutinib-resistance in chronic lymphocytic leukemia (CLL), and the effect of the inhibition of this axis as a basis for identifying new strategies in CLL treatment." (PMID 34771616, 2021).
Fever (5 papers, 2012 to 2026). Body temperature elevated above the normal range. "In C. albicans, the expression of HSP genes is activated by the heat shock transcription factor 1 (Hsf1), which becomes phosphorylated in response to temperature elevations, including thermal transitions that mimic fever." (PMID 32437438, 2020). "We have used this model to show that the thermal adaptation system displays perfect adaptation, that it retains a transient molecular memory, and that Hsf1 is activated during thermal transitions that mimic fever." (PMID 22448221, 2012).
Hepatic steatosis (5 papers, 2018 to 2024). Steatosis is a term used to denote lipid accumulation within hepatocytes. "Usp39 deficiency results in an isoform of Hsf1 that undergoes degradation by nonsense-mediated mRNA decay, which in turn leads to impaired autophagy and to hepatic steatosis." (PMID 37923718, 2023). "Importantly, our results suggest that loss of Usp39 induces hepatic steatosis partially by impairing Hsf1-regulated autophagy." (PMID 37923718, 2023). "Collectively, these results suggest that hepatic steatosis due to Usp39 depletion is partially mediated by Hsf1 downregulation and the subsequent impairment in autophagy." (PMID 37923718, 2023). "A recent study documented that hyperhomocysteinemia promoted Mdm2-mediated ubiquitination of HSF1 to activate hepatic NLRP3 inflammasome, thus leading to hepatic steatosis." (PMID 39277582, 2024). "Moreover, HSF1 promotes tumour cell proliferation and metabolism by cytoprotective pathways and it can also accelerate HCC development and act as a key determinant of HCC development by regulating hepatic steatosis and metabolic syndrome." (PMID 29898735, 2018).
Infertility (5 papers, 2019 to 2025). "Knock-out phenotype observed for the master regulator of HSP proteins, HSF1.HSF1 knock out (Hsf1tm1Ijb/Hsf1tm1Ijb) in female mice causes infertility (J:58383, J:65267); abnormal female meiosis and abnormal meiotic spindle assembly checkpoint (J:175085)." (PMID 40422207, 2025). "Cooperation between hsf1 and hsf2 is vital for fertility in both sexes, with inactivation of these genes resulting in failures in gametogenesis and infertility." (PMID 40427320, 2025). "The frequencies of genotypes CC, CA and AA for rs78202224 (C/A) for HSF1 gene in all infertile, azoospermic and asthenozoospermic cases were 71.4%, 26.6 % and 2.0%; 71.7%, 26.6% and 1.7% and 69.9%, 26.5% and 3.6 % and in controls it was 71.2%, 25.9% and 2.9%,respectively." (PMID 35540693, 2021). "However, data on genetic variations in HSF1, HSF2 and UBE2I genes for infertility in males is scanty." (PMID 35540693, 2021). "However, none of theSNPs in HSF1 and HSF2 genes is linked with infertility in men in the study cohort." (PMID 35540693, 2021).
leukemia (5 papers, 2017 to 2025). A malignant (clonal) hematologic disorder, involving hematopoietic stem cells and characterized by the presence of primitive or atypical myeloid or lymphoid cells in the bone marrow and the blood. "In the results from single–cell sequencing data form CancerSEA, HSF1 was significantly related to various aspects of leukemogenesis, and a remarkable association was observed for HSF1 and leukemia stem cell metastasis in AML." (PMID 36069792, 2022). "In AML, HSF1 may contribute to leukemia stem cells metastasis and is associated with malignant characteristic." (PMID 36069792, 2022). "This signature was the worst preserved in LAML, which was especially evident when only selected genes potentially regulated by HSF1 (i.e., with detected binding of HSF1) were analyzed, indicating a different HSF1 action in leukemia and adenocarcinoma." (PMID 36010586, 2022). "The leukemogenesis mechanisms of HSF1 are a multifactor regulatory process that is involved in inflammatory states, leukemia stem cell metastasis and related signaling pathways." (PMID 36069792, 2022). "Collectively, our results identify a novel mechanism by which oridonin induces rapid degradation of BCR-ABL as well as a novel pharmaceutical activator of HSF1 that represents a promising treatment for leukemia." (PMID 28128329, 2017). "Given the dependency of human LSCs on HSF1, we tested if a small molecule HSF1 inhibitor could specifically kill leukemia cells, while sparing normal HSPCs." (PMID 36245043, 2022). "Analysis of mice with fully developed leukemia showed that acute Hsf1 ablation reduced the LSC frequencies and increased the frequencies of CD11b+ more mature and differentiated leukemia cells." (PMID 36245043, 2022). "SISU-102 clearly inhibited the expression of the HSF1 targets, HSP90 and SDHC, and HSF1 itself, in a dose-dependent manner and strongly suppressed the growth and OCRs of murine MLL-AF9 Hsf1fl/flcreER leukemia cells and human MV4–11 and NOMO-1 AML cells." (PMID 36245043, 2022). "HSF1 may affect immune cells in order to regulate the immune state in AML and influence leukemia cell growth, metastasis, and AML patient survival, but its mechanisms remain to be validated in vitro and in vivo." (PMID 36069792, 2022). "In the absence of Hsf1, the development of MLL-AF9 leukemia in vivo was significantly delayed, suggesting that HSF1 is required for the initiation of MLL-AF9–induced AML." (PMID 36245043, 2022). "Our results reveal the role of oridonin as a small molecule proteostasis regulator that activates endogeneous HSF1 and support the potential clinical use of oridonin for BCR-ABL-expressing leukemia by inducing BCR-ABL degradation rather than inhibiting tyrosine kinase activity." (PMID 28128329, 2017).
liver fibrosis (5 papers, 2018 to 2023). "And miR-455-3p can inhibit liver fibrosis by alleviating HSC activation through suppressing heat shock transcription factor 1 (HSF1) expression." (PMID 33708992, 2021). "All above, SalA can increase the expression and deacetylation of HSF1 both in vivo and in vitro, and attenuate liver fibrosis." (PMID 30455644, 2018). "The molecular mechanism of SalA against BDL-induced liver fibrosis involves SIRT1 deacetylating HSF1, resulting in a decrease in ER stress and liver fibrosis." (PMID 30455644, 2018). "We found that the increased expression of SIRT1 leads to the deacetylation of HSF1 and up-regulation of heat shock proteins, which can relive liver fibrosis through inhibition of ER stress." (PMID 30455644, 2018). "In this study, we discovered that HSF1 regulates ER stress in liver fibrosis, and SalA regulates HSF1 by up-regulating SIRT1." (PMID 30455644, 2018). "Salvianolic acid may prevent liver fibrosis brought on by bile duct ligation by triggering the SIRT1/heat shock factor 1 (HSF1) signaling pathway." (PMID 36985782, 2023). "Moreover, we determined that the SIRT1/HSF1 pathway is involved in the protective effects of SalA against BDL- induced liver fibrosis." (PMID 30455644, 2018). "Similarly, SalA significantly inversed the PDGF-BB-induced inhibition of deacetylation of HSF1 in vitro, which was related to the protective effect of SalA against ER stress and liver fibrosis." (PMID 30455644, 2018). "However, the effect of these HSF1 regulation mechanisms in BDL-induced liver fibrosis remains to be further explored." (PMID 30455644, 2018). "The objective of this study was to investigate the effect of SIRT1-mediated inhibition of ER stress in bile duct ligation (BDL)-induced liver fibrosis, and to explore the effect of salvianolic acid A (SalA) on BDL-induced liver fibrosis through SIRT1/heat shock factor 1 (HSF1) signaling." (PMID 30455644, 2018). "In addition, HSF1 is also involved in the process of liver fibrosis, and the mechanism may be that mir-455-3p reduces the activation of hepatic stellate cells and liver fibrosis by inhibiting the expression of HSF1." (PMID 35265144, 2022). "Additionally, miR-455-3p reduces liver fibrosis and HSC activation by inhibiting the expression of HSF1, and miR-199a-3p exacerbates hepatic fibrosis by inhibiting the expression of caveolin-2 and triggering the TGF-β pathway." (PMID 34867446, 2021).
metastatic tumors (5 papers, 2017 to 2025). "Moreover, only in ER-positive cancers an elevated HSF1 level is associated with metastatic disease." (PMID 34783649, 2021). "Nevertheless, the data from TCGA showing a correlation between increasing levels of HSF1 and metastatic disease in ER-positive breast cancers support the observations from the in vitro model that HSF1 may affect migration." (PMID 34783649, 2021). "Interestingly, HSF1 protein levels were higher in mCRPC cells isolated from spine (SM1), kidney (KM1) and liver (LM1) metastatic tumors than in 22RV1 cells, indicating that HSF1 expression is increased in mCRPC cells." (PMID 41028522, 2025).
neuroblastoma (5 papers, 2011 to 2017). Neuroblastoma (NB) is the most common solid, extracranial childhood tumor. "Here, we discover aberrant HSF1 degradation by aggregated α-synuclein (or α-synuclein-induced proteotoxic stress) in transfected neuroblastoma cells." (PMID 26503960, 2016). "HSF1 is strongly depleted following quercetin treatment and this effect appeared more marked in neuroblastoma cells." (PMID 24212658, 2011). "As for quercetin treatment, neuroblastoma cells were the most sensitive to HSF1 silencing effect." (PMID 24212658, 2011). "Moreover, a strict correspondence between the quercetin concentrations necessary to cause both HSP inhibition and doxorubicin sensitizing effect was observed, suggesting that neuroblastoma cell' resistance to doxorubicin treatment might be due to high levels of HSPs, under the control of HSF1." (PMID 24212658, 2011). "To determine whether α-synuclein (α-syn, herein after) aggregation altered HSF1 expression levels, we transiently transfected SH-SY5Y neuroblastoma and HEK293 cells with GFP-tagged wild-type (WT) α-syn (GFP-α-syn WT) or GFP-tagged A53T mutant α-syn (GFP-α-syn A53T)." (PMID 26503960, 2016). "Therefore, the negative control exerted by DUSP26 on HSF4, altogether with the inverse correlation in the expression of these two proteins in neuroblastoma, may contribute to repress HSF4 activity in neuroblastoma and its potential crosstalk with HSF1." (PMID 24212658, 2011).
tauopathies (5 papers, 2014 to 2022). "Our data clearly demonstrated that overexpression of HSF1 activated Hsp70 expression, alleviated ER stress and tauopathy, prevented retinal inflammation, and protected retinal neuronal cells from death and dysfunction in a mouse model of retinal ischemia." (PMID 30884523, 2019). "We investigated how UPR effector proteins such as CHOP and HSP70 a5 (BiP/GRP78) regulate HSF1 to potentiate a vicious cycle active in the cellular tauopathy model (N2a-TauRDΔK280)." (PMID 28678786, 2017). "We implicate CHOP activation in the UPR pathway as one of key players that partially contributes to HSF1 degradation in tauopathy." (PMID 28678786, 2017). "Nevertheless, how ER stress affects HSF1-mediated stress response is poorly understood, particularly in the contexts of neurons and tauopathy." (PMID 28678786, 2017). "In the aged HSF1+/- hippocampus, there were two major p-Tau bands at ~64- and ~68- kDa with a minor band at ~72 kDa, similar to the pattern observed in human tauopathy brain." (PMID 28678786, 2017). "It is notable that this was a short treatment with PU-H71 late in the disease process provided benefit, raising the possibility that HSF1 activation could be beneficial for therapy of tauopathies later in the disease course." (PMID 36271092, 2022). "In addition to regulation of tauopathy, we found that HSF1 overexpression attenuated production of inflammatory molecules such as iNos, Cxcl10, and Il-1β and prevented leukocyte attachment and infiltration, which is a hallmark of vascular inflammation." (PMID 30884523, 2019). "Taken together, these results identify that a dramatic loss of HSF1 protein is an early and progressive event that may precede PERK activation and NFTs formation in murine tauopathy and human AD." (PMID 28678786, 2017). "Consequently, reduced steady state level of HSF1 is likely to trigger permanent PERK-CHOP activation that reversely facilitates HSF1 loss, leading to tau hyperphosphorylation in tauopathy." (PMID 28678786, 2017). "Tauopathy is characterized by a build-up of tau aggregates, and thus the notion that HSF1 could also be degraded by tau aggregation stands as an intriguing possibility." (PMID 28678786, 2017). "In addition to the role of autophagy-lysosomal activity on the HSF1 protein turnover, given highly poly-ubiquitinated HSF1 protein in N2a-TauRD ΔK280, it is necessary to investigate the involvement of ubiquitin-proteasome system in tauopathy as we did in synucleinopathy." (PMID 28678786, 2017). "Together these data suggest that targeting the dysfunctional HSF1-driven HSP chaperone system with PU-H71 significantly reduces oTau-induced pathology and neurodegeneration in AstTau, accentuating the involvement of HSPs in tauopathies." (PMID 36271092, 2022). "To determine whether expression of HSF1 protein and UPR marker proteins was altered in the mouse tauopathy models, we looked at the brains of PS19 (tau P301S) mouse and rTg(tauP301L)4510 mouse overexpressing P301S and P301L mutant tau, respectively." (PMID 28678786, 2017).
colon adenocarcinoma (4 papers, 2017 to 2024). "Moreover, HSF1 expression level was correlated with tumor stage and nodal metastasis status in colon adenocarcinoma (COAD) by GEPIA2, TISIDB, UALCAN database." (PMID 35006040, 2022).
ischemia (4 papers, 2012 to 2023). A hypoperfusion of the BLOOD through an organ or tissue caused by a PATHOLOGIC CONSTRICTION or obstruction of its BLOOD VESSELS, or an absence of BLOOD CIRCULATION. "The novel finding of this study is that a deficiency in HSF1 results in an impairment in neovascularization after ischemia." (PMID 22655083, 2012). "To investigate whether HSF1 is implicated in retinal ischemia, we used a mouse model of ischemia-reperfusion (IR), in which retinal ischemia is induced by acute elevation of intraocular pressure, and examined the expression of HSF1." (PMID 30884523, 2019). "Considering that recent studies have revealed the contribution of HSP90 or heme oxygenase-1 to neovascularization, there is a possibility that changes in HSP expression within limb tissue in response to ischemia may in part be associated with the reduced angiogenic potential in the HSF1-KO mice." (PMID 22655083, 2012). "During ischemia, Hsf1 can be released from the cytoplasmic Hsp90 complex, and Hsf1 forms its own trimer, which has DNA binding ability, enters the nucleus, binds to DNA and promotes the expression of Hsp70 protein family members." (PMID 37055533, 2023). "The mobilization of BM-derived Sca-1- and c-kit-positive cells in peripheral blood after ischemia was significantly lower in the HSF1-KO mice than in the WT mice." (PMID 22655083, 2012). "The mobilization of BM-derived stem/progenitor cells was blunted in HSF1-KO mice after the induction of ischemia, and the recruitment of BM cells from HSF1-KO mice into ischemic tissue also decreased." (PMID 22655083, 2012). "It keeps unclear how the enhanced HSF1 effects the expression of HSPs, that are known to play a role of angiogenesis in response to ischemia." (PMID 22655083, 2012). "We also observed increased levels of SDF-1 in the plasma and limb tissue in the HSF1-KO mice after ischemia, which was similar to WT mice." (PMID 22655083, 2012). "All of these findings suggest that, in the HSF1-KO mice, impaired neovascularization in response to ischemia might be attributable, at least in part, to the dysfunction of BM cells." (PMID 22655083, 2012). "Although further experiments are required to examine in detail how HSF1 affects the number and function of BM-derived stem/progenitor cells, HSF1 likely plays a role in ischemia-induced angiogenesis by regulating the mobilization and recruitment of BM stem/progenitor cells." (PMID 22655083, 2012). "To further confirm our hypothesis that HSF1 contributes to ischemia-induced angiogenesis by regulating the mobilization and recruitment of BM-derived cells, we induced hindlimb ischemia in the chimeric mice after mismatched BMT." (PMID 22655083, 2012). "Given that the expression of HSPs is mainly regulated by HSF1, it is possible that HSF1 regulates the mobilization and recruitment of BM-derived stem/progenitor and contributes, at least in part, to angiogenesis in response to ischemia." (PMID 22655083, 2012). "Interestingly, we found the increased expression of HSF1 in the limb tissue after ischemia." (PMID 22655083, 2012). "Moreover, it remains to be seen whether HSF1 affects the function of other types of cells, including endothelial cells and myoblasts, for angiogenesis within the limb tissue after the induction of ischemia." (PMID 22655083, 2012). "We found that the VEGF levels in the plasma and limb tissue in the HSF1-KO mice increased after inducing limb ischemia, and that VEGF levels in the plasma and ischemic tissue did not significantly differ between HSF1-KO and WT mice 3 days after ischemia." (PMID 22655083, 2012).
ovarian tumors (4 papers, 2016 to 2025). "HSF1 mRNA levels are increased in various cancers, including breast, endometrial, and ovarian tumors, often due to HSF1 gene amplification and mutations in splicing factors." (PMID 40287736, 2025). "Upon analysis of various patient data sets, we find that HSF1 is frequently overexpressed in ovarian tumor samples." (PMID 27997575, 2016). "Two distinct data sets of matched ovarian tumor tissue vs. normal tissue show that HSF1 mRNA expression is significantly higher in tumor tissue." (PMID 27997575, 2016). "However, sequencing for copy-number changes is routine for clinical assessment of ovarian tumors, making HSF1–MYC co-amplification more easily accessible as a clinical biomarker for HGSOC." (PMID 39831777, 2025). "Additional targets of the HSF1 and MYC complex could offer some insights to their functions in ovarian tumors." (PMID 39831777, 2025).